PIK3CA (phosphatidylinositol-4,5-bisphosphate 3-kinase catalytic subunit alpha)
Diseases named in the same sentence as PIK3CA in open-access papers (continued):
Sharing a sentence is not in itself a finding about the gene and the disease.
lung carcinoma (228 papers, 2009 to 2026). "PIK3CA mutations have been reported in various cancer types, including colorectal, breast, liver, brain, stomach, and lung cancer." (PMID 40666093, 2025). "The presence of PIK3CA mutations in lung cancer has several clinical implications, including worse prognosis due to increased tumor aggressiveness and metastatic potential." (PMID 39199653, 2024). "For instance, in lung cancer and esophageal cancer, a few studies revealed that mutations in PIK3CA were markedly more frequent in SCC than in adenocarcinoma." (PMID 38616230, 2024). "The PI3K signalling pathway is deregulated in a broad spectrum of human cancers, and PIK3CA is frequently mutated or amplified in many human cancers, including breast, colon, gastric, cervical, prostate, and lung cancer." (PMID 38787171, 2024). "Mutations in the PIK3CA gene have been implicated in various types of cancer, including lung cancer, with a frequency of 2–4% in NSCLC cases." (PMID 39199653, 2024). "For instance, in a study involving both LUSC and lung adenocarcinoma tissues from lung cancer patients, PIK3CA mutations were found in 9% of LUSC patients and 0% of adenocarcinoma patients." (PMID 38616230, 2024). "In lung cancer, mutations and amplifications in the PIK3CA gene are frequently observed, particularly in squamous cell carcinoma, and significantly contribute to tumorigenesis and disease progression." (PMID 39682234, 2024). "Over activity of the p110α catalytic subunit of PIP3 as a result of activating mutations majorly in the helical and kinase domain of the PIK3CA gene was found to be a main culprit in lung cancer progression." (PMID 37568796, 2023). "Analysis of a 1122 EGFR-mutant patient cohort revealed that multiple co-occurring oncogenic events are present in most advanced-stage EGFR-mutant lung cancers, including PIK3CA mutation." (PMID 37553597, 2023). "The Chinese cohort had significantly lower frequencies of PIK3CA mutations in breast and stomach cancers, but markedly higher PIK3CA mutation frequencies in large intestine, kidney and lung cancers than the COSMIC cohort." (PMID 35778737, 2022). "The comparative studies revealed that the Chinese cohort had a significantly higher frequency of PIK3CA mutations in large intestine, kidney, and lung cancers, but a markedly lower mutation frequency in breast and stomach cancers than the COSMIC cohort." (PMID 35778737, 2022). "The mutation of PIK3CA gene can lead to abnormal enhancement of the catalytic activity of PI3Ks and promote the carcinogenesis of cells in lung cancer." (PMID 35831792, 2022). "PIK3CA, the gene encoding the catalytic subunit of the PI3Kα isoform, is frequently mutated in various human cancers, including breast, ovarian and lung cancers." (PMID 34279440, 2021). "EGFR, KRAS, and PIK3CA gene mutations have a correlation with the clinical characteristics of lung cancer patients, which should be further accepted and improved to enhance the efficacy for personalized cancer treatment." (PMID 34217313, 2021). "In this study, we analyzed the mutation status of EGFR, KRAS, and PIK3CA in different types of lung cancer patients." (PMID 34217313, 2021). "Few studies have systematically evaluated the relationship between the mutation status of EGFR, KRAS, and PIK3CA and lung cancer patients, especially among patients with different types of lung cancer." (PMID 34217313, 2021). "Gene insertions, deletions, and somatic missense mutations in Pik3ca are frequent in colon, breast, brain, liver, stomach, and lung cancers." (PMID 34356110, 2021). "Mutations of PIK3CA in lung cancer are uncommon, being prevalently detected in SCC histology, while its amplification is conversely frequently found." (PMID 33807876, 2021).
lung carcinoma (continued). "In contrast to the mutual exclusivity of many oncogenic drivers in lung cancers, PIK3CA mutations frequently coexist with other oncogenic driver mutations, especially EGFR and KRAS." (PMID 33363040, 2020). "Another study involving more than 700 lung cancer samples reported the PIK3CA mutation frequency to be ca. 2%." (PMID 31905960, 2019). "To this aim we suppressed AKT1 and AKT2 expression in an established lung cancer cell line (NCI-H460) that harbours an activating mutation of PIK3CA (E545K) as reported." (PMID 27880728, 2017). "PIK3CA mutation rates vary widely across different cancer types, being reported in 2-7% of lung cancers but up to 40% of breast and colorectal cancers." (PMID 27765909, 2016). "Few data have been provided so far concerning the roles of Notch1 in lung adenocarcinoma harboring mutations in other lung cancer driver genes, such as PIK3CA or EGFR (Epidermal Growth Factor Receptor)." (PMID 27847554, 2016). "Although single PIK3CA mutations have been reported 17, the majority of lung cancer with PIK3CA mutations had another cocurrent driver mutation in previous studies." (PMID 27554588, 2016). "Activation of mTOR, AKT and loss of PTEN have each been associated with a poorer prognosis in lung cancer patients, however an association between PIK3CA mutation status and prognosis has been controversial." (PMID 27765909, 2016). "In summary, PIK3CA mutation represents a subset of lung carcinoma with a prevalence of 2.8% in Chinese population." (PMID 27554588, 2016). "BRAF mutations accompanied by a PIK3CA mutation were observed in 2 of 33 (6.1 %) BRAF-mutated lung cancers, 4 of 34 (12 %) BRAF-mutated CRCs, and 2 of 67 (3.0 %) BRAF-mutated melanomas." (PMID 26498038, 2015). "Here we present the genetic and phenotypic analysis of a PIK3CA mutated subgroup within a cohort of 1144 NSCLC patients consecutively collected over a period of two years in a molecular screening network for lung cancer." (PMID 25473901, 2015). "Preclinical data showed that introducing activated PIK3CA mutations into EGFR-mutated lung cancer cell lines confers resistance to EGFR-TKIs." (PMID 26175928, 2015). "Further, PIK3CA-mutated patients had a significantly higher incidence of malignancy prior to lung cancer (p<0.001)." (PMID 25473901, 2015). "Activating PIK3CA p.H1047R mutation has also been shown to cooperate with BRAF p.V600E mutation to promote progression of benign lung tumors to lung cancers." (PMID 26498038, 2015). "The observation of the high frequency of the occurrence of PIK3CA-mutated lung cancer as secondary malignancy needs further investigation." (PMID 25473901, 2015). "PIK3CA mutations have been detected in about 5% of EGFR-mutant lung cancers with acquired resistance to EGFR-TKI therapy." (PMID 23936763, 2013). "PIK3CA is mutated in approximately 25% of breast, 32% of colorectal, 30% of endometrial, 27% of brain, 25% of gastric, 4% of lung cancers." (PMID 23006971, 2012). "It is of note that IPA analysis of DEGs in PIK3CA-transduced BEAS-2B cells retrieved several functions linked to ADCs and SCCs, indicating that the adoptive expression of active PIK3CA elicit a transcriptional response that is associated to lung cancer." (PMID 22363436, 2012). "In clinical studies of metastatic colon cancer, patients with wild type K-ras, B-raf and PIK3CA genes gain benefit from cetuximab therapy, whilst lung cancer patients with mutations in exons 19 and 21 of the EGFR gene benefit from Iressa or Tarceva therapy." (PMID 22935382, 2012). "While mutations in PIK3CA are relatively infrequent in lung cancer, PIK3CA copy number gain has been reported in 33.1% of squamous cell lung cancer and in 6.2% adeno lung cancer in one large series." (PMID 22355357, 2012). "Recent studies have shown in the lung cancers with mutant PIK3CA, there are also mutations at other driver oncogenes, such as EGFR, KRAS, BRAF, MEK, and anaplastic lymphoma kinase (ALK)." (PMID 23006971, 2012).
lung carcinoma (continued). "Recently, mutations in PIK3CA were identified in ~5% of EGFR mutant lung cancers that developed acquired EGFR TKI resistance." (PMID 22970367, 2012). "Inhibitors of the PI3K pathways are presently in development including specific inhibitors of p110alpha that have demonstrated efficacy in engineered preclinical models of lung cancer harboring activating point mutations in PIK3CA." (PMID 21303542, 2011). "Mutation or amplification of PIK3CA has been reported and associated with lung cancer progression." (PMID 36499051, 2022). "PIK3CA mutation frequencies of large intestine, kidney and lung cancers in the Chinese cohort were significantly higher than those in the COSMIC cohort, while the mutation frequencies of breast and stomach cancers in the Chinese cohort were notably lower than the COSMIC cohort." (PMID 35778737, 2022). "Similarly, inhibiting EZH2 has been reported to enhance the sensitivity of the pan‐PI3K inhibitor copanlisib in lung cancer cells harbouring mutated or amplified PIK3CA when the manuscript was in preparation." (PMID 35604910, 2022). "In addition, the PIK3CA gene mutation status in exons E9 and E20 was associated with sample type, as well as lung cancer type." (PMID 34217313, 2021). "The incidence of PIK3CA gene mutation in nonsmall cell lung cancer is 2%-5%." (PMID 33997043, 2021). "Studies in lung cancer suggested that PIK3CA amplification was associated with higher TMB." (PMID 33996530, 2020). "Similarly, the pathogenic significance of PIK3CA is also uncertain, judging from the unusually infrequent detection of mutations in lung cancer (2% in adenocarcinoma and 5% in SqKs)." (PMID 32441866, 2020). "The frequency of PIK3CA gene mutation in lung cancer varies significantly." (PMID 31905960, 2019). "The prognostic relevance of PIK3CA mutations has been investigated in various solid tumors, and PIK3CA mutations are generally associated with an unfavorable prognosis in patients with colorectal or lung cancer." (PMID 30115035, 2018). "PIK3CA mutations co-exist mostly with KRAS mutations in lung cancer." (PMID 28212572, 2017). "Similarly, the concordance rates between tumor tissue sample and cfDNA for detecting PIK3CA exon 9/20 mutations were as high as 97%-100% in lung cancer." (PMID 27336598, 2016). "Although the test could not allow the detection of all variants, our mutation detection method covered more than 90% of the PIK3CA mutations in all lung cancer histology of the COSMIC database." (PMID 27734950, 2016). "Notably, when such activating PIK3CA mutations are introduced into EGFR-mutant lung cancer cells, they impart a partial resistance to TKIs." (PMID 25962919, 2015). "In lung cancer, copy number gains of PIK3CA were found to be exclusive to PIK3CA mutation, implying that both alterations may have oncogenic potential to promote carcinogenesis in the lung." (PMID 24533074, 2014). "Clinical trials are ongoing in lung cancers carrying PIK3CA, BRAF or KRAS mutations." (PMID 24236184, 2013). "PIK3CA mutations have been already identified in a broad range of human cancers at varying frequencies, including liver (36%), breast (26%), colon (25%), urothelial (13%), ovarian (9%), gastric (7%), brain (6%), and lung cancer (2%) as well as leukaemia (1%)." (PMID 22363598, 2012). "Mutations or copy number gains of PIK3CA, the gene encoding p110α, have been described in lung cancer, and a limitation of our study is that the PIK3CA genetic status is unknown in the tumor specimens of our cohorts." (PMID 22355357, 2012). "In addition to PIK3CA mutations, PIK3CA amplification was frequently found in lung cancer, and promoted lung tumorigenesis through overactivation of PI3K/Akt signaling pathway." (PMID 21507233, 2011). "Some of the conditions when Tyr176 phosphorylation of AKT is not required for AKT activation could be; 1) Presence of constitutively active PIK3CA mutations, observed in colorectal, glioblastomas, gastric breast and lung cancers." (PMID 20333297, 2010).
lung carcinoma (continued). "In order to test the hypothesis that a PIK3CA-activating mutation drives resistance to osimertinib, we introduced the PIK3CA H1047R (hereafter referred to as PIK3CAm) variant in three lung cancer cell line models using a CRISPR/Cas9 technology: PC9, PC9-T790M and HCC827." (PMID 33741979, 2021). "The most common sites of PIK3CA mutations included H1047R/L (8 mutations total), E545K/G (4 mutations), and E542K (3 mutations), all of which represent previously reported hotspot mutation sites in other cancers such as prostate cancer, lung cancer, melanoma, and breast cancer." (PMID 31235758, 2019). "Mutation in PIK3CA signaling pathways may induce resistance to EGFR‐TKIs of lung cancer patients." (PMID 27554588, 2016). "However, PIK3CA mutated lung cancer frequently develops in patients with prior malignancies." (PMID 25473901, 2015). "In addition, lung cancer cell lines harboring PIK3CA or PTEN mutations were sensitive to dual PIK3CA/mTOR inhibitors, which raises the hope that patients with mutations in the PI3K pathway may benefit from this type of targeted therapy in the future." (PMID 26068980, 2015). "PIK3CA mutations can promote cellular survival and proliferation, which contribute to resistance to EGFR-TKIs in lung cancer." (PMID 41189942, 2025). "For other prevalent actionable mutation in lung cancer KRAS, PIK3CA, FGFR3, MET, NRAS, and RET demonstrated 100 % specificity with varied sensitivities around 50 %." (PMID 40503459, 2025). "For instance, miR-183-5p is posited to act as a tumor suppressor in lung cancer through its inhibitory action on PIK3CA." (PMID 39759146, 2024). "Among lung cancers with EGFR-sensitive mutations, 3.5% harbor the PIK3CA mutation; however, its influence on EGFR-TKI efficacy in EGFR-mutated lung cancer is controversial." (PMID 38398169, 2024). "The mutation of RBM10 co-exists with the known lung cancer target genes KRAS, EGFR, and PIK3CA, among others." (PMID 37509501, 2023). "PIK3CA and ErbB2 gene co-variation most associated with primary EGFR-TKIs resistance in EGFR-mutant lung cancer patients." (PMID 37553597, 2023). "Our previous clinic data also suggested that the PIK3CA co-variation, accounting for 16.67% of EGFR-mutant lung cancer patients, was associated with poorer PFS, only 4.57 months, after EGFR-TKI treatment." (PMID 37553597, 2023). "Dactolisib combined with selumetinib resulted in the synergistic action of lung carcinoma with KRAS and PIK3CA mutations." (PMID 36539659, 2022). "The PIK3CA regulatory axis is identified as a potentially effective therapeutic strategy for lung cancer, considering that this signaling pathway is also targeted by other significant miRNAs, such as miR-21-5p and miR-34c." (PMID 36556276, 2022).
lung carcinoma (continued). "In another genomic study of BM of various origin, several potentially actionable genomic alterations were associated with lung cancer BM, including AKT1, AURKA, CDK6, EGFR, MEK1, MET, and PIK3CA gene amplifications and CDKN2A deletions." (PMID 36561283, 2022). "Other frequently mutated genes in the tumor tissue samples used in our lung cancer study were FLT3 (altered in 87% of the samples), KDR (84%), CSF1R (72%), PIK3CA (59%), and ERBB4 (53%)." (PMID 35330454, 2022). "It is reported miR-183-5p has joined in the proceeding of various cancers, for example, miR-183-5p can play a cancer suppression role in lung cancer by regulating PIK3CA." (PMID 35435136, 2022). "Our group has recently profiled a large Nova Scotian lung cancer patient cohort for major driver mutations in lung cancer (EGFR, ALK, KRAS, BRAF, and PIK3CA)." (PMID 33956842, 2021). "We observed a positive correlation of PIK3CA aberrations with smoking status (P = 1.7E-02), inconsistent with a previous study in Japanese lung cancer patients." (PMID 32034196, 2020). "Lung cancer is well established as a highly heterogeneous tumor that harbors various gene alterations including mutations in EGFR, KRAS, BRAF, PD-L1, and PIK3CA, as well as ALK rearrangement and HER2 amplification." (PMID 33411683, 2020). "We first sought to assess the impact of PIK3CA mutations in models mimicking clinical scenarios featuring MET constitutive activation, such as gastric or lung cancer." (PMID 28532501, 2017). "The frequency of PIK3CA, NRAS, HRAS, and PTEN mutations was higher in cfDNA than in lung cancer tissue in the cBioPortal database." (PMID 29290998, 2017). "In lung cancer cell lines, 37% of squamous cell harbored PIK3CA amplification and they were sensitive to PI3K inhibitor GDC-0941 with less than 1μmol/L of IC50." (PMID 27016421, 2016). "Activation of the PI3K pathway, generally as result of PIK3CA amplification, has been demonstrated in 12% cases of lung cancer, 32% cases of head and neck cancer, and 24% cases of ovarian cancer." (PMID 27016421, 2016). "Current study evaluated the genetic variants of PIK3CA, AKT1, and AKT2, all of which are genes in PI3K/AKT pathway, to discover their potential associations with the occurrence of RP in lung cancer patients with radiotherapy." (PMID 26645682, 2016). "In a multinational Lung Cancer Consortium study, PIK3CA was detected in approximately 1% of untreated cases." (PMID 27304188, 2016).